FGFR2 (fibroblast growth factor receptor 2)
Diseases named in the same sentence as FGFR2 in open-access papers (continued):
Sharing a sentence is not in itself a finding about the gene and the disease.
cholangiocarcinoma (continued). "For example, FDA has approved orally administered Truseltiq (infigratinib) from Brisbane, California-based QED Therapeutics, Inc., under the accelerated approval program for treating patients with locally advanced or metastatic cholangiocarcinoma (CCA) harboring an FGFR2 fusion or rearrangement." (PMID 36213130, 2022). "Futibatinib was further tested in a dose expansion phase on 45 patients with cholangiocarcinoma (41 with ICCA) harboring FGFR2-aberrations, 28 of them (62%) FGFR2-fusions and 17 (38%) other FGF-FGFR aberrations." (PMID 35444941, 2022). "Infigratinib is an inhibitor of fibroblast growth factor receptor 2 (FGFR2) and has shown promising therapeutic effects in previously treated FGFR2-mutant cholangiocarcinoma patients." (PMID 35443744, 2022). "Pemigatinib (an FGFR2 inhibitor) demonstrated activity in previously treated advanced cholangiocarcinoma based on a phase 2 trial and was approved by the US FDA in 2020, but only 10–15% of patients with iCCA have the FGFR2 fusion gene." (PMID 34359777, 2021). "Several FGFR2 inhibitors (infigratinib, TAS120, pemigatinib) are currently being evaluated in several ongoing randomized trials in advanced cholangiocarcinoma with FGFR rearrangements, versus cisplatin-gemcitabine in the first-line setting." (PMID 33660222, 2021). "Currently, erdafitinib and pemigatinib are approved for use in the United States for metastatic urothelial carcinoma with FGFR2 or FGFR3 aberrations and for cholangiocarcinoma with an FGFR2 rearrangement, respectively." (PMID 34247193, 2021). "Fusions of FGFR2 with the citron Rho-interacting kinase (CIT) were identified in non-small cell lung cancer and cholangiocarcinoma." (PMID 34207779, 2021). "There are several identified binding partners for FGFR2, some of them are TACC3 and CCDC6 in cholangiocarcinoma and BICC1 in hepatocarcinoma and colorectal cancer." (PMID 34830836, 2021). "In a trial exploring futibatinib in previously treated cholangiocarcinoma patients with FGFR alterations, 20/28 patients carrying FGFR2 fusions experienced tumor shrinkage and 7/28 confirmed PR." (PMID 32962091, 2020). "Other FGFR inhibitors, such as BGJ398, showed an objective response rate of 14.8% (18.8% FGFR2 fusions only) and disease control rate of 75.4% (83.3% FGFR2 fusions only) in patients with FGFR-altered advanced cholangiocarcinoma." (PMID 32411236, 2020). "In early clinical trials, promising results were reported in patients who show FGFR2 amplification in gastric cancer and in patients with FGFR2 and FGFR3 translocations in cholangiocarcinoma and urothelial cancers, respectively." (PMID 32325878, 2020). "Genes elevated in cholangiocarcinomas included higher expression of the cholangiocyte gene Beta‐defensin 1 (DEFB1) and FGFR2." (PMID 33332768, 2020). "Among cholangiocarcinoma patients with FGFR fusions or rearrangements, 35.5% achieved an objective response when treated with second-line pemigatinib, an oral inhibitor of FGFR1, FGFR2, and FGFR3." (PMID 40558236, 2025). "Importantly for cholangiocarcinoma, PTPN9 has been shown to dephosphorylate FGFR2 at the activation loop (pY656/657) and to synergize with the FGFR inhibitor pemigatinib, supporting a role for PTPN9 in modulating FGFR-TKI efficacy." (PMID 41275311, 2025). "Pemigatinib, a small molecule inhibitor of FGFR1–3, has been approved in the US for treatment of unresectable cholangiocarcinoma with FGFR2 alterations, while erdafitinib, pan-FGFR inhibitor, is indicated for metastatic urothelial carcinoma with FGFR2 and FGFR3 alterations." (PMID 40393028, 2025). "ERBB2 amplification was the most common predictive marker in gastroesophageal adenocarcinoma, and recent targeted therapy approvals and guideline updates had a significant impact for patients with cholangiocarcinoma and actionable findings in IDH1 (11.2%), FGFR2 (8.1%), or BRAF (1.8%)." (PMID 37682776, 2024).
cholangiocarcinoma (continued). "Unlike urothelial cancers, cholangiocarcinoma demonstrates high rates of FGFR2 fusions or rearrangements." (PMID 37681152, 2023). "A phase I/II study ReFocus (NCT04526106) was conducted to evaluate RLY-4008 in patients (n = 38) with cholangiocarcinoma harboring FGFR2 fusions/rearrangements who did not receive prior FGFR inhibitors." (PMID 37681152, 2023). "FGFR2 rearrangements are clinically actionable genetic alterations, as supported by evidence of clinical benefits with targeting the FGF/FGFR signaling pathways in patients with cholangiocarcinoma containing FGFR2 rearrangements." (PMID 36127767, 2023). "The FGFR2-LGSN transcript has been previously detected in cholangiocarcinoma, however it is not yet functionally characterized; detected here in ovarian cancer." (PMID 36009413, 2022). "For pemigatinib, all observed responses were limited to FGFR2 fusion-positive cholangiocellular carcinoma and no confirmed responses were seen in other FGFR alterations." (PMID 36231142, 2022). "Published reports for FGFR2-rearranged cholangiocarcinoma indicate that non-partner rearrangements are reported in ~10% of all cases." (PMID 35871236, 2022). "The 5′ RTK fusion FGFR2-LGSN that was verified here in the ovarian cancer sample OC11 has been previously detected in cholangiocarcinoma; however, it has not yet been functionally characterized." (PMID 36009413, 2022). "On the Phase II study of BGJ398 in patients with FGFR-altered advanced cholangiocarcinoma, BGJ398 showed 18.8% overall response rate and 83.3% disease control rate in patients carrying FGFR2 fusion with manageable toxicities actively supporting its further biologic and clinical investigation." (PMID 33692336, 2021). "In particular, through the FDA accelerated approval process, erdafitinib is indicated to treat metastatic urothelial carcinoma with FGFR2 and FGFR3 alterations, and pemigatinib is indicated to treat unresectable cholangiocarcinoma with fusions or rearrangements of FGFR2." (PMID 34204560, 2021). "Thus far, erdafitinib and pemigatinib are the first FDA-approved FGFR selective inhibitors for treating urothelial cancer with FGFR2 or FGFR3 alterations, and cholangiocarcinoma with FGFR2 fusions and rearrangements, respectively." (PMID 33898310, 2021). "Intrachromosomal rearrangements, which account for about 50% of FGFR2 fusions in intrahepatic cholangiocarcinoma, can also lead to false-negative results of FISH analysis." (PMID 32962091, 2020). "Clinical activity has been reported in non-randomised studies of FGFR2 translocated cholangiocarcinoma with TAS-120 and pemigatinib." (PMID 35582593, 2019). "SOX9 has been identified as a crucial regulator in cholangiocarcinoma (CCA), where it promotes plays a significant role in enhancing the expression of FGF7 and FGFR2." (PMID 38491511, 2024). "Interestingly, this study also noted cholangiocarcinoma (CCA) FFPE clinical specimens with FGFR2 RNA fusions without the 20 top actionable DNA NOTCH-1 mutations." (PMID 36213130, 2022). "Studies have shown that upwards of 60% of cholangiocarcinoma (CCA) contain such aberrations, including those in isocitrate dehydrogenase-1 (IDH1), fibroblast growth factor receptor-2 (FGFR2), and neurotrophic tyrosine receptor kinase (NTRK)." (PMID 35626165, 2022). "Fibroblast growth factor receptor 2 (FGFR2) gene fusions are bona fide oncogenic drivers in 10–15% of intrahepatic cholangiocarcinoma (CCA), yet currently there are no cell lines publically available to study endogenous FGFR2 gene fusions." (PMID 32252259, 2020). "FGFR2 fusions or rearrangements have been identified in 10-16% of all intrahepatic CCA and are thought to serve as a pathway of resistance for a number of nonresectable and refractory cases of cholangiocarcinoma." (PMID 37954763, 2023).
gastric cancer (209 papers, 2007 to 2026). A primary or metastatic malignant neoplasm involving the stomach. "A kinome-wide CRISPR/Cas9 screen in FGFR2-amplified gastric cancer cell lines (e.g., KatoIII) demonstrated that loss of focal adhesion kinase (ILK) and suppression of EGFR/HER2 signaling increased sensitivity to FGFR inhibition." (PMID 41227318, 2025). "We previously reported that some diffuse types of gastric cancer showed K-samII amplification, which encodes FGFR2, and FGFR2 inhibitors were therapeutically promising for gastric carcinoma with FGFR2 amplification using several gastric cancer cell lines." (PMID 41226813, 2025). "Particularly, the extremely malignant type of gastric cancer is associated with FGFR2 amplification; however, few useful drugs have yet been clinically approved for cancers with FGFR2 amplification." (PMID 41226813, 2025). "The abnormal activation of FGFR2 through mutations, gene amplification, or overexpression is a significant factor in the development of several types of cancer, including gastric cancer." (PMID 39195304, 2024). "In fact, FGFR2 gene amplification and gene alteration is one of the leading causes of gastric cancers, making FGFR2 a coveted target for the development of therapeutics." (PMID 39329537, 2024). "For instance, FGFR1 amplifications were notably prevalent in breast and lung cancer, while FGFR2 mutations were frequently in endometrial and gastric cancers (GCs)." (PMID 39138146, 2024). "In patients with early-stage gastric cancer, FGFR2 amplifications were noted to be associated with a higher-grade tumor stage, more frequent lymph node involvement, and inferior OS." (PMID 38255923, 2024). "Alterations in fibroblast growth factor receptor 2 (FGFR-2) have been linked to gastric cancer, intrahepatic cholangiocarcinoma, and endometrial uterine cancer." (PMID 39077220, 2024). "Increasing evidence reported that FGFR2 was associated with cancers, such as endometrial uterus cancer, gastric cancer, and ovarian cancer (37, –, 39)." (PMID 37358427, 2023). "FGFR2 is also subjected to gene amplification or mutations in gastric cancer, colorectal cancer, endometrial cancer, and melanomas." (PMID 37750089, 2023). "In the primary gastric carcinoma group, FGFR2 amplification was associated with poor prognosis (p = 0.005)." (PMID 36416959, 2023). "Accumulating evidence indicates the significance of FGFR2 in the tumorigenesis and progression of gastric cancer (GC); genomic aberrations in FGFR2 have been linked to one of the most frequently occurring oncogenic aberrations." (PMID 35342406, 2022). "In our study, somatic CDH1 mutations and FGFR2 CNV gains were identified to enrich in the younger gastric cancer patients." (PMID 35498538, 2022). "Although previous studies have reported FGFR2 amplification in gastric cancers and its association with a poor outcome, our study has shown for the first time that FGFR2 amplification is significantly associated with peritoneal seeding." (PMID 36292044, 2022). "Mutations of FGFR2 are present in 12% of endometrial carcinomas, and approximately 10% of gastric cancer cases are associated with amplification and/or mutation of FGFR2; moreover, the degree of amplification is closely related to prognosis." (PMID 33352931, 2020). "Approximately 1.2–9% of patients with gastric cancer harbour FGFR2 amplifications associated with increased tumour cell proliferation." (PMID 31601997, 2019). "Overexpression and gene amplification of fibroblast growth factor receptors 2 (FGFR2) has been associated with poor outcome in gastric cancer." (PMID 28852882, 2018). "FGFR2 amplification was also associated with proven poor prognostic factors of gastric cancer, including poor performance status and bone metastases." (PMID 27802183, 2017). "Consistent with current findings, previous studies have indicated an association between high-grade histology and FGFR2 amplification in resectable gastric cancer." (PMID 27802183, 2017).
gastric cancer (continued). "FGFR2 amplification has been identified in gastric cancers and found to be associated with a poor prognosis." (PMID 28460431, 2017). "What’s more, the organoid-derived tumors with FGFR2 overexpression had histologic features of gastric cancer and caused metastases to the lung." (PMID 28629429, 2017). "FGFR2 amplification occurs in 5–10% of gastric cancers, with an association to poor diagnosis and tumor metastasis." (PMID 28629429, 2017). "FGFR2-activating mutations have been identified in 12% endometrial carcinomas and ~10% gastric cancers shown to harbor FGFR2 amplification and mutations." (PMID 27029060, 2016). "Our studies revealed that loss of FGFR2 expression is also implicated in resistance-associated EMT induction in SNU-16 gastric cancer cells, in which the FGFR2IIIb isoform dominates." (PMID 25407459, 2016). "Our data indicated that both FGFR1 and FGFR2 amplification were associated with poor survival in breast, lung, and gastric cancers." (PMID 25171497, 2014). "Activating somatic mutations of FGFR2 have been reported in some cancers including lung squamous cell carcinoma, gastric cancer, cervical carcinoma, and endometrial carcinoma, implicating its role in cancer development." (PMID 23300950, 2013). "FGFR2 mutations are observed in 12% of endometrial cancers but are reportedly rare in gastric cancers." (PMID 22240789, 2012). "Mutations in the FGFR2 often occur in endometrial, non-small cell lung, and gastric cancers." (PMID 41415030, 2025). "Consequently, in the context of gastric cancer, FGFR2 amplification has been classified as a Level D1 mutation." (PMID 41216191, 2025). "FGFR2’s dysregulated activity, whether through amplification, mutations, or heightened expression, is closely linked to the development and progression of gastric cancer." (PMID 39195304, 2024). "Somatic mutations CDH1 and copy number gains of FGFR2 were identified to enrich in the younger gastric cancer patients, which may contribute to the worse prognosis of early-onset gastric cancer patients." (PMID 35498538, 2022). "In human malignancies, amplifications of FGF3 and FGFR2 are linked to breast and gastric cancer." (PMID 35996584, 2022). "We hypothesized that FGFR2 could be associated with peritoneal seeding and studied 360 advanced gastric carcinoma patients; 222 (61.7%) were male, 246 (73.7%) had poorly differentiated histology, and 175 (48.6%) presented with peritoneal seeding." (PMID 36292044, 2022). "FGFR2 rearrangements have been detected in 10–15% of intrahepatic cholangiocarcinomas, amplifications in up to 15% of gastric cancers and point mutations in about 10% of endometrial cancers; moreover, FGFR2 amplification has also a prognostic significance in gastric cancers." (PMID 34178989, 2021). "FGFR2 mutations are most common in endometrioid cancers and gastric cancers." (PMID 34068954, 2021). "Gastric cancer with FGFR2 amplification is significantly associated with poor survival outcome." (PMID 33178597, 2020). "The increased phosphorylation of the Ephrin 3B (Eph3B) receptor was found to be associated with acquired FGFR resistance in SNU-16 (FGFR2 amplified) gastric cancer cells, which could be reversed with small molecule inhibitors of Eph3B." (PMID 35582593, 2019). "For example, JNJ-42756493, a potent inhibitor of the tyrosine kinase activities of the four FGFR family members, may be beneficial for treating gastric cancer with FGFR2 amplification and those that harbour the G636C-FGFR4 mutation." (PMID 31601997, 2019). "Similarly, FGFR2 amplification in breast and gastric cancers is associated with poorer prognosis and high sensitivity to FGFR inhibitors." (PMID 30326595, 2018). "In gastric cancer, FGFR2 amplification is associated with poorer overall survival." (PMID 28835367, 2017).
gastric cancer (continued). "In the present study, we aimed to investigate the association of FGFR2 amplification with the clinicopathologic features and prognostic significance in patients with unresectable gastric cancer treated with fluoropyrimidine and platinum (FP) as first-line chemotherapy." (PMID 27802183, 2017). "Also, approximately 10% of cases of gastric cancer are associated with FGFR2 amplification and/or mutation; in particular amplification is suggestive of a poor prognosis and more widespread disease." (PMID 28030802, 2017). "Furthermore, a few studies examined the clinicopathologic features of FGFR2-amplified gastric cancer and showed that FGFR2 amplification was associated with poorer prognosis." (PMID 27802183, 2017). "Considering that miR125b regulates HER2 in gastric cancer, we would expect further comprehensive miRNA assays may reveal the underlying mechanism of transcriptional regulation of FGFR2 in EGJ adenocarcinoma." (PMID 26933914, 2016). "FGFR2 amplification occurs at a high frequency in gastric cancer (GC) and has been proven to be closely associated with poor prognosis and insensitivity to chemotherapy or immunotherapy." (PMID 41870032, 2026). "Among several types of FGFR alterations, FGFR2 amplification has been identified in endometrial and gastric cancers (GC) and is associated with poor prognosis." (PMID 36292044, 2022). "Although some studies reported that FGFR2 was overexpressed in 31.1% of GC patients and might be associated with vascular invasion, FGFR2 amplification enhanced the sensitivity of regorafenib in gastric cancer and colorectal cancer." (PMID 35187167, 2022). "Fibroblast growth factor 2 (FGFR2) amplification, occurring in ~2–9% of gastric cancers (GC), is associated with poor overall survival." (PMID 28122360, 2017). "Furthermore, we found that FGFR2 amplification was related to a higher risk group by using our prognostic model that was developed by combining multiple clinicopathologic features of advanced gastric cancer." (PMID 27802183, 2017). "It potently suppresses FGF7-induced receptor phosphorylation and proliferation in FGFR2-IIIb-overexpressing gastric cancer cells (e. g., SNU16)." (PMID 41584352, 2026). "In gastric cancer, profound spatial heterogeneity has been observed in FGFR2-IIIb expression between biopsies, surgical specimens, and metastatic sites." (PMID 41584352, 2026). "Clinical observations have shown that patients with gastric cancer featuring FGFR2 amplification respond to futibatinib treatment." (PMID 41216191, 2025). "In another setting, gastric cancer, FGFR2 amplification occurs in 2–9%, more commonly in diffuse-type histology and younger patients." (PMID 41153346, 2025). "In this review, we aim to explore the effects of FGFR2 overexpression in gastric cancer, the utility of targeting FGFR2 in the treatment of gastric cancer, and the challenges in using this biomarker." (PMID 41303727, 2025). "This combined approach identified a correlation between FGFR2 mRNA expression and gene amplification in a cohort of 1036 gastric cancer patients." (PMID 41303727, 2025). "A phase II clinical trial (NCT04189445) demonstrated tumor shrinkage in 58% of patients with FGFR2-amplified gastric cancer, but the objective response rate (ORR) varied between 17,9% and 26%." (PMID 41303727, 2025). "Subsequently, the oral CHK1 inhibitor BBI-2779 was further applied in a mouse gastric cancer model containing FGFR2 ecDNA, confirming that BBI-2779 can inhibit gastric cancer growth and cause sustained tumor regression in mice." (PMID 41030947, 2025). "Studies have shown that FGFR2 amplification occurs in gastric cancer with a probability of 3%–16%, and FGFR2 amplification is associated with advanced diffuse gastric cancer and a poorer prognosis." (PMID 40296904, 2025). "In HT1080 fibrosarcoma cells, RHAMM regulates cell proliferation through a β-catenin/c-myc signaling axis, and CD44 can influence gastric cancer cell growth by interacting with FGFR2 and c-myc." (PMID 40178908, 2025).